COL8A1 (collagen type VIII alpha 1 chain)
Diseases named in the same sentence as COL8A1 in open-access papers (continued):
Sharing a sentence is not in itself a finding about the gene and the disease.
neurological disorders (1 paper, 2022). "Indeed, identified genes are implicated in viral (SEC14L1, JMJD6, SRSF2, TMPRSS2, MX1, MX2) bacterial (COL8A1, SPIRE1), and neurological disorders (MFSD11, METTL23, CTTNBP2, BACE2, IMPA2, MPPE1 and GNAL), or in the functions of the Golgi complex (MGAT5B), organelle where viral envelope is occurred." (PMID 35581286, 2022).
COL8A1 also shares sentences with these, for which no sentence is quoted: ameloblastoma (2 papers); glaucoma (2); psoriatic arthritis (2); Atopic Dermatitis (1); atrial fibrillation (1); benign adenomas (1); breast tumor (1); clear cell renal cell carcinoma (1); connective tissue disorder (1); craniopharyngioma (1); diabetic nephropathy (1); dilated cardiomyopathy (1); esophageal squamous cell carcinoma (1); fibrosis (1); Fuchs endothelial corneal dystrophy (1); Fuchs' endothelial dystrophy (1); head and neck squamous cell carcinoma (1); ischemia (1); Knobloch syndrome (1); lymph node metastasis (1); medulloblastoma (1); Myocardial fibrosis (1); non-small cell lung carcinoma (1); Obesity (1); ovarian carcinoma (1); pancreatic adenocarcinoma (1); primary open angle glaucoma (1); Pruritus (1); pterygium (1); pulmonary fibrosis (1).
A further 13 diseases each share a sentence with COL8A1 in 1 paper.